BTC (betacellulin)
Diseases named in the same sentence as BTC in open-access papers (continued):
Sharing a sentence is not in itself a finding about the gene and the disease.
tumor (12 papers, 2014 to 2025). "It was found that triple therapy can increase the level of CCL 28 and the number of CD 8+ and CD 4+ T cells in peripheral blood and reduce the level of betacellulin, which inhibits tumor angiogenesis and progression." (PMID 38022559, 2023). "In our recent publication, we have shown that the genetic deletion of a single ligand of the ERBB family, BTC, also led to a reduced tumor burden in Kras mice, which was due to decreased EGFR‐signaling." (PMID 37341059, 2023). "BTC expression showed a significant correlation with patient age, tumor stage, histological grade, and lymph metastasis status, especially in patients with lymph metastatic OSCC whose BTC levels were significantly reduced." (PMID 35846125, 2022). "However, our RT-qPCR analysis demonstrated relatively high BTC mRNA expression in the HuH7 cell line, suggesting a spatially restricted role for BTC within the tumor microenvironment (TME)." (PMID 40906438, 2025). "According to the clinical data collected from our hospital and in vitro functional studies, we found that BTC may play a vital role in inhibition of OSCC progression as a tumor-suppressor gene." (PMID 35846125, 2022). "Furthermore, we analyzed the associations between the clinicopathological variables and BTC expression in 38 OSCC patients, and we found that the BTC expression was related to histological grade, N classification, tumor stage, and metastasis." (PMID 35846125, 2022). "BTC was expressed in tumors and involved in tumor growth progression." (PMID 24629040, 2014). "Betacellulin (BTC) proteins are ligands for the EGFR/ERBB4 ligand, with established literature showing that BTC overexpression by HCC cells and EGFR expression by tumor-associated endothelial cells collaboratively enhance tumor vascularity via paracrine signaling." (PMID 40906438, 2025). "The probability of interaction between tumor cells and fibroblast receptor-ligand pairs was higher than that of thyroid cells, especially in TGFB1/ACVR1/TGFBR1, FGF18/FGFR1, BTC/EGFR, BMP8A/BMPR1A/BMPR2, and BMP8A/BMPR1A/BMPR2." (PMID 37733241, 2023). "Of the EGFR ligands, amphiregulin, BTC, EGF, and TGFα were expressed in the cytoplasm of 50%, 76%, 70%, and 73% of the tumours respectively." (PMID 30899442, 2019). "Considering all the patients showing downregulation of total HER4 in their tumor tissue, in 82% of these NRG4 was also downregulation and in 86% one or more of the EGFR-shared ligands (HB-EGF, epiregulin, betacellulin) was upregulated." (PMID 24728052, 2014). "The expression of betacellulin, which belongs to the EGF family, in HCC cells has been shown to have a significant positive correlation to EGFR expression by tumor endothelial cells, suggesting a potential paracrine signaling pathway to induce tumor angiogenesis." (PMID 38173713, 2023). "On the contrary, we found that upregulation of BTC could inhibit cell proliferation and EMT-mediated metastasis in OSCC, which might be due to the endogenous differences between distinct tumor types." (PMID 35846125, 2022). "Thus, in addition to overexpression of the EGF receptor, its ligands epidermal growth factor (EGF), transforming growth factor-α TGF-α, amphiregulin (AR), betacellulin (BTC), heparin-binding EGF-like growth factor (HB-EGF), and epiregulin (EREG) have been reported to be upregulated in tumor tissues." (PMID 31921216, 2019). "However, it is difficult to extrapolate these results to the in vivo setting since EGFR might respond not only to EGF but also to TGF-α, AR, EPGN, BTC, HB-EGF and EREG, which are also increased in tumor tissues." (PMID 31921216, 2019). "The EGFR ligands: epidermal growth factor (EGF), transforming growth factor-α (TGFA), heparin-binding EGF-like growth factor (HBEGF), amphiregulin (AREG), beta-cellulin (BTC), epiregulin (EREG) and epigen (EPGN), may increase tumor growth, invasion, and metastasis through EGFR activation." (PMID 27669890, 2016).
infection (3 papers, 2016 to 2025). The state of being infected such as from the introduction of a foreign agent such as serum, vaccine, antigenic substance or organism. "Infection with P. aeruginosa resulted in a significant increase of AP activity in the cell supernatant after 2 and 4 h in comparison to control, showing a correlation with enhanced betacellulin shedding." (PMID 35163191, 2022). "Our quantitative PCR data showed that three ligands, HB-EGF, AREG and EREG, displayed significant up-regulation at 60 min after infection with strain RS218, while the transcriptional levels of EGF, BTC and TGFα remained unchanged during the infection." (PMID 27711202, 2016). "Significantly high levels of betacellulin and RANKL expression after one month of infection with SDAV and MHV-JHM may contribute to astrocyte-mediated repair and T-cell regulation." (PMID 40358160, 2025). "The results showed that the triple deletion mutant was able to induce significant up-regulation of AREG and EREG after 60 min, while there was no up-regulation of HB-EGF, as well as EGF, BTC, and TGFα, after infection with the triple deletion mutant." (PMID 27711202, 2016).
BTC also shares sentences with these, for which no sentence is quoted: Hyperglycemia (2 papers); E. coli infection (1); lung adenocarcinoma (1); macular edema (1); ovarian tumors (1); proliferative diabetic retinopathy (1); psoriasis (1); retinopathy (1); schizophrenia (1).